RARA (retinoic acid receptor alpha)
Diseases named in the same sentence as RARA in open-access papers (continued):
Sharing a sentence is not in itself a finding about the gene and the disease.
acute promyelocytic leukemia (continued). "We also discuss how altered condensate formation contributes to malignant transformation of hematopoietic cells, as described for promyelocytic leukemia protein (PML) in PML::RARA-driven acute promyelocytic leukemia (APL) and other myeloid malignancies." (PMID 37388925, 2023). "As a curative frontline treatment for APL, ATO-ATRA molecularly targets the oncogenic fusion protein; promyelocytic leukaemia–retinoic acid receptor α (PML::RARA)." (PMID 36834572, 2023). "PML/RARA (promyelocytic leukemia/retinoic acid receptor A) fusion protein can block the differentiation and maturation of granulocytes, which is the main cause of APL (acute promyelocytic leukemia)." (PMID 35433636, 2022). "ANXA8 upregulation was first described in promyelocytic leukemia, harboring a PML-RARA fusion, in which dysregulation of RARA gene caused such overexpression." (PMID 36247003, 2022). "Molecular analysis with nested RT–PCR revealed a bcr3 isoform of the promyelocytic leukemia/retinoic acid receptor alpha (PML–RARA) transcript and a FLT3 ITD." (PMID 36278522, 2022). "According to FAB classification, AML-M3 is a subtype of AML characterized by the presence of promyelocytic leukemia-retinoic acid receptor alpha (PML-RARA) genes fusion." (PMID 36144542, 2022). "As an agonist of RARα, Am80 has already been approved for the treatment of acute promyelocytic leukemia." (PMID 35237277, 2022). "PML/RARα-regulated miR-181a/b cluster targets the tumor suppressor RASSF1A in acute promyelocytic leukemia." (PMID 35366954, 2022). "The two adult patients with FIP1L1::RARA fusion were diagnosed as acute promyelocytic leukemia (APL)." (PMID 35819517, 2022). "They found that a small percentage of cases remained, and these were categorized under AML M3 as per FAB classification, which is now categorized as acute promyelocytic leukemia (APL) with PML/RARA under AML-RGA." (PMID 33973643, 2021). "Previous studies have primarily focused on the retinoic acid signaling pathway and how it is interfered with by promyelocytic leukemia/retinoic acid receptor-α (PML/RARα) fusion protein." (PMID 33901013, 2021). "Retinoic acid receptor alpha (RARA) regulates transcription in a ligand-dependent manner; diseases associated with acute promyelocytic leukemia." (PMID 34828279, 2021). "Acute promyelocytic leukemia (APL) patients with PLZF/RARA fusion protein are largely resistant to all-trans retinoic acid (ATRA) treatment and with poor prognosis." (PMID 34454635, 2021). "SY-1425 is an oral first-in-class selective retinoic acid receptor alpha (RARα) agonist investigated as maintenance therapy or in refractory acute promyelocytic leukemia." (PMID 33668555, 2021). "Acute promyelocytic leukemia (APL) is characterized by a specific chromosome translocation involving RARα and its fusion partners." (PMID 34117212, 2021). "It is demonstrated that USP18 stabilizes PML/RARα protein and inhibits cell apoptosis in all-trans-retinoic acid (RA)-sensitive and RA-resistant acute promyelocytic leukemia (APL) cells." (PMID 34454635, 2021). "Fluorescence in situ hybridization was positive for promyelocytic leukemia/retinoic acid receptor alpha." (PMID 32590818, 2020). "Patients with a subtype of acute myeloid leukemia (AML), known as acute promyelocytic leukemia, show the fusion of the retinoic acid receptor alpha (RARA), with the promyelocytic leukemia gene." (PMID 33195511, 2020). "The first cancer showing ANXA8 upregulation was reported in acute promyelocytic leukemia (APL), which induces the differentiation arrest of promyelocytes due to defective RA signaling caused by RARA fusion genes as the PML-RARA gene." (PMID 32823855, 2020). "A microfluidic assay for the detection of promyelocytic leukemia (PML)-retinoic acid receptor α (RARα) fusion protein was developed." (PMID 33255664, 2020).
acute promyelocytic leukemia (continued). "Acute promyelocytic leukemia (APL), a less common form of AML, is characterized by the formation of the promyelocytic leukemia/retinoic acid receptor α (PML/RARα) fusion protein, which causes many of the features of the disease." (PMID 32676504, 2020). "PML/RARa, the hallmark fusion protein of acute promyelocytic leukemia, undergoes cleavage to generate an NLS bearing truncated RARα (NLS-RARα)." (PMID 32624581, 2020). "Fluorescence in situ hybridization for promyelocytic leukemia/retinoic acid receptor alpha (PML-RARα) was positive in 96% of cells tested; consistent with the hypogranular variant of acute promyelocytic anemia." (PMID 32590818, 2020). "Tretinoin, a derivative of Vitamin A, can function via targeting the retinoic acid receptor alpha (RARα)-mediated signals to alter the cell apoptosis, and has been used as a medication to treat acute promyelocytic leukemia (APL) for decades." (PMID 31501521, 2020). "Acute promyelocytic leukemia subtype M3 (AML M3) is a subtype of AML characterized by the presence of promyelocytic leukemia-retinoic acid receptor alpha (PML-RARA) genes fusion." (PMID 32243411, 2020). "APL is mostly caused by a reciprocal chromosomal translocation between the retinoic acid receptor alpha gene (RARα) and promyelocytic leukemia (PML), and this affects a number of cellular processes, including senescence, RNA processing and apoptosis." (PMID 31330838, 2019). "In acute promyelocytic leukemia or adult T-cell lymphoma, arsenic-induced, SUMO-triggered ubiquitination and proteasomal destruction of driver oncoproteins (PML/RARA and Tax, respectively) were shown to be the underlying mechanism for therapy response." (PMID 31431473, 2019). "Promyelocytic leukemia-retinoic acid receptor α (PML-RARa) sets the cellular landscape of acute promyelocytic leukemia (APL) by repressing the transcription of RARa target genes and disrupting PML-NBs." (PMID 31635329, 2019). "RARA rearrangements are well-known to be involved in acute promyelocytic leukemia (APL), but RARG rearrangements can also resemble this kind of leukemia." (PMID 31709264, 2019). "This catabolic pathway is strikingly similar to the recently uncovered mechanism of therapy-induced PML/RARA degradation in acute promyelocytic leukemia and therapy-induced Tax oncoprotein degradation in adult T-cell lymphoma." (PMID 31431473, 2019). "ZnO nanowalls-based electrochemical biosensors have also been used to monitor promyelocytic leukemia and retinoic acid receptor alpha (PML/RARA) fusion genes that can cause acute promyelocytic leukemia (PML)." (PMID 31540160, 2019). "Exposure to IRC117539 promotes AR sumoylation and ubiquitination, reminiscent of therapy-induced PML/RARA degradation in acute promyelocytic leukemia." (PMID 31431473, 2019). "ANXA8 upregulation was found upregulated for the first time in acute promyelocytic leukemia (APL) with repressed wild-type RARA transcriptional function due to dominant negative RARA fusion proteins as PML-RARA." (PMID 30678048, 2019). "Acute promyelocytic leukemia (APL) is characterized by expression of the promyelocytic leukemiahetinoic acid receptor alpha gene (PML/RARa;PR)." (PMID 30607328, 2018). "Subsequently, it was verified that USP37 expression modulated the oncogenic fusion protein PLZF/RARA stability and cell transformation potential in PLZF/RARA-associated acute promyelocytic leukemia." (PMID 30482232, 2018). "Acute promyelocytic leukemia (APL) is a special kind of acute myeloid leukemia (AML) characterized by the presence of PML/RARα fusion gene located on chromosome 15 and chromosome 17, respectively." (PMID 30200136, 2018). "This mutation leads to the formation of two fusion genes (oncogenes), promyelocytic leukemia– retinoic acid receptor alpha (PML–RARα) and RARα–PML." (PMID 30237857, 2018). "The NRs in the cancer group include RARA (acute promyelocytic leukemia), NR1H4 (hepatocellular carcinoma), ESR1 (breast cancer), and AR (prostate cancer)." (PMID 29065888, 2017).
acute promyelocytic leukemia (continued). "All-trans retinoic acid (ATRA) and/or arsenic trioxide (ATO) administration leads to granulocytic maturation and/or apoptosis of acute promyelocytic leukemia (APL) cells mainly by targeting promyelocytic leukemia/retinoic acid receptor alpha (PML/RARα)." (PMID 28492552, 2017). "RUNX2, ALX3 and RARA are also central in multiple sequences and related to diseases in both human and mouse: cleidocranial dysplasia, frontonasal dysplasia 1 and acute promyelocytic leukemia respectively." (PMID 29161290, 2017). "A distinct subtype of AML is acute promyelocytic leukemia (APL), which is associated with a translocation involving the retinoic acid receptor A (RARA) on chromosome 17." (PMID 29021535, 2017). "Aside from those patients with chronic myeloid leukemia (CML) induced by wild-type BCR-ABL fusion protein or those with acute promyelocytic leukemia (APL) caused by reciprocal chromosomal translocation of the retinoic acid receptor α (RARα) gene, most patients have a poor prognosis." (PMID 29312995, 2017). "For example, in acute promyelocytic leukemia patients, the RARα gene is fused with a number of alternative partner genes such as PML, promyelocytic leukemia zinc finger and nucleophosmin." (PMID 28035062, 2017). "Since molecular therapy of the promyelocytic leukemia-retinoic acid receptor alpha (PML-RARα) in acute promyelocytic leukemia (APL) is well-established, we will limit our review to novel agents for non-APL AML." (PMID 28851395, 2017). "Retinoic acid receptors(RARa), an important regulator of the terminal differentiation of acute promyelocytic leukemia cells, is directly phosphorylates by CaMKIIγ, and this phosphorylation inhibits the RARa transcriptional activity." (PMID 29088844, 2017). "Acute Promyelocytic Leukemia (APL) is a subtype of Acute Myeloid Leukemia (AML) with the characteristic chromosomal translocation involving retinoic acid receptor alpha (RARA) gene and Promyelocytic leukemia protein (PML) gene." (PMID 27929140, 2016). "RARα forms driver fusion proteins in acute promyelocytic leukemia, for which Pin1 suppression is used as a treatment." (PMID 27540857, 2016). "The involvement of ZBTB16 with retinoid receptors is also suggested by the association of a chromosomal translocation to a rare variant of acute promyelocytic leukemia (APL), which fuses the ZBTB16 (PLZF) protein to retinoic acid receptor (RARA)." (PMID 27513748, 2016). "Rapid diagnosis of acute promyelocytic leukemia (APL) with promyelocytic leukemia-retinoic acid receptor alpha (PML-RARa) contributes to a highly effective therapy with all-trans retinoic acid (ATRA)." (PMID 25815789, 2015). "USP37 also plays a role in stabilizing tumor suppressor p27 in medulloblastoma cells and promyelocytic leukemia zinc finger and retinoic acid receptor alpha (PLZF-RARA) oncogenic fusion protein in Acute promyelocytic leukemia." (PMID 25347529, 2014). "RARα is associated with differentiation therapy for human acute promyelocytic leukemia (APL)." (PMID 24473166, 2014). "Promyelocytic leukemia (PML) gene was discovered as a fusion partner of human retinoic acid receptor alpha (RARα) gene, resulting in PML-RARα fusion protein that is critical for pathogenesis of acute promyelocytic leukemia (APL)." (PMID 25419843, 2014). "For example, chronic myelogenous leukemia (CML) is characterized by the Philadelphia chromosome and the resulting BCR/ABL1 gene fusion, while acute promyelocytic leukemia (APL) is characterized by RARA rearrangement." (PMID 23637631, 2013). "Promyelocytic leukemia-RARα is, like PML, phosphorylated by ERK1/2 in response to As2O3 and, then, highly conjugated to SUMO2/3, since it retains two of the three major PML SUMOylation sites at K65 and K160." (PMID 23734343, 2013). "First evidence came from the PML/RARA oncoprotein responsible of acute promyelocytic leukemia (APL)." (PMID 23847762, 2013).
acute promyelocytic leukemia (continued). "An attempt was made to use functionalized graphene oxide (GO) to detect the Promyelocytic leukemia/Retinoic acid receptor α fusion gene (PML/RARα fusion gene), a marker gene of acute promyelocytic leukemia." (PMID 23787474, 2013). "Promyelocytic leukemia-retinoic acid receptor alpha (PML-RARα) expression in acute promyelocytic leukemia (APL) impairs transforming growth factor beta (TGFβ) signaling, leading to cell growth advantage." (PMID 22053203, 2011). "HDACs mediate the function of oncogenic translocations in many malignancies including promyelocytic (PML)-retinoic acid receptor alpha (RARα) in acute promyelocytic leukemia." (PMID 20929526, 2010). "The only well-defined mutation that involves RARs is a reciprocal translocation that occurs between the RARα (human chromosome 17) and the promyelocytic leukemia (human chromosome 15) loci in some forms of acute promyelocytic leukemia (APL)." (PMID 21566745, 2008). "The DLP 3D printer MiiCraft Prime could be used to produce microfluidic structures for the detection of the fusion protein PML::RARA for the diagnosis of acute promyelocytic leukemia quickly and cost-effectively." (PMID 39859217, 2025). "Although RARα was initially shown to be an oncogenic driver as a fusion product of promyelocytic leukemia (PML) and RARA genes in acute promyelocytic leukemia (APL) 9, recent reports have demonstrated that native RARα possesses oncogenic properties itself 10-14." (PMID 39744424, 2025). "The underlying mechanism(s) by which the PML::RARA fusion protein initiates acute promyelocytic leukemia is not yet clear." (PMID 38648485, 2024). "Recently, the interaction between dyslipidemia-related genes and hematologic malignancy genes has been reported; for instance, the PML/RARα fusion protein and peroxisome proliferator-activated receptor-α have a synergistic effect on acute promyelocytic leukemia." (PMID 37384286, 2023). "In an acute promyelocytic leukemia (APL) model (PML/RARα), green tea treatment reduced blast percentages (CD34 and/or CD117) in the bone marrow and spleen possibly through the induction of apoptosis and reduction in the CXCR4/HIF-1α signaling pathway in response to a decrease in ROS levels." (PMID 37513933, 2023). "However, it is interesting to note that a recent study demonstrated the stabilizing effects of YOD1 on oncogenic PML/RARα frequently found in promyelocytic leukemia (APL)." (PMID 37454155, 2023). "Am80 has been licensed for the management of acute promyelocytic leukemia as an agonist of RARα." (PMID 36768908, 2023). "In this manuscript, we report torque teno mini virus (TTMV) as a cause of acute promyelocytic leukemia (APL) lacking PML::RARA in a 3-year-old boy." (PMID 36591487, 2022). "Promyelocytic leukemia (PML)-RARA is the most frequently expressed fusion protein." (PMID 33742137, 2021). "The last two issues allow to overcome the RT-qPCR limitations in monitoring several fusion transcripts, such as both canonical and atypical BCR–ABL1 breakpoints in CML patients and PML/RARA in acute promyelocytic leukemia (APL), guiding the therapeutic strategy." (PMID 34771634, 2021). "Promyelocytic leukemia with retinoic acid receptor alpha (PML-RARα)-fusion-mediated NEAT1 transcriptional repression might impair the myelopoiesis of acute promyelocytic leukemia cells." (PMID 34502451, 2021). "Studies reported that knocking out TRIB3 inhibited tumor formation and cancer progression, disrupting TRIB3–SQSTM1 or TRIB3–PML/RARα interactions through specific peptides, which is a potential strategy for treatment of certain solid cancers and acute promyelocytic leukemia." (PMID 32874132, 2020).
acute promyelocytic leukemia (continued). "Acute promyelocytic leukemia (APL) is characterized by the presence of a chromosomal translocation between the retinoic acid receptor-alpha (RARα) gene on chromosome 17 and the promyelocytic leukemia protein (PML) gene on chromosome 15, resulting in the PML-RARα fusion gene." (PMID 32168763, 2020). "Acute Promyelocytic Leukemia (APL) is a subset of Acute Myeloid Leukemia (AML) that is clinically characterized by gene rearrangements involving the Retinoic Acid Receptor Alpha (RARα) and by the infiltration of bone marrow and/or blood by leukemic cells that resemble promyelocytes." (PMID 31415632, 2019). "Nowadays, it is clinically used to treat acute promyelocytic leukemia (APL) by targeting PML/RARA." (PMID 29535630, 2018). "Promyelocytic leukemia (PML) proteins, which fuse with retinoic acid receptor alpha and induce tumors such as acute promyelocytic leukemia, were shown to be down-regulated by arsenic trioxide, and PML proteins are tightly involved in NLRP3 inflammasome activation." (PMID 30209319, 2018). "Furthermore, defective RA/RARα signaling is involved in the pathogenesis of acute promyelocytic leukemia due to a failure in differentiation of promyelocytes." (PMID 28230720, 2017). "We have previously shown that a specific promyelocytic leukemia-retinoic acid receptor alpha (PML-RARA) DNA vaccine combined with all-trans retinoic acid (ATRA) increases the number of long term survivors with enhanced immune responses in a mouse model of acute promyelocytic leukemia (APL)." (PMID 26378812, 2015). "Besides our report, USP18 has been reported to directly maintain oncogene stability such as the chimeric, dominant-negative-acting transcription factor promyelocytic leukemia gene (PML)/RARa during acute promyelocytic leukemia development." (PMID 24884733, 2014). "PLZF was first recognized to fuse with retinoic acid receptor RARa in acute promyelocytic leukemia." (PMID 22558183, 2012). "Acute promyelocytic leukemia (APL) is a subtype of acute myeloid leukemia characterized by the presence of the promyelocytic leukemia-retinoic acid receptor alpha (PML::RARA) fusion gene." (PMID 42131682, 2026). "Most cases of acute promyelocytic leukemia (APL) are driven by the PML::RARA fusion gene, which is sensitive to differentiation induction therapy comprising of all-trans retinoic acid (ATRA) and arsenic trioxide (ATO)." (PMID 40386562, 2025). "In 2022, A study demonstrated that PML/RARα fusion proteins that drive chromosomal translocation production in acute promyelocytic leukemia (APL) are assembled by LLPS into nucleosomal structures." (PMID 38347544, 2024). "Reprogramming of hematopoietic stem and progenitor cells by PML::RARA leads to aberrant self-renewal, a precursor to the development of APL (acute promyelocytic leukemia)." (PMID 38648485, 2024). "Acute promyelocytic leukemia (APL) is characterized by rearrangements of the retinoic acid receptor, RARα, which makes all-trans retinoic acid (ATRA) highly effective in the treatment of this disease, inducing promyelocytes differentiation." (PMID 38877119, 2024). "Acute promyelocytic leukemia (APL) is initiated by the PML::RARA fusion gene in greater than 95% of cases." (PMID 38648485, 2024). "In acute promyelocytic leukemia (APL) with PML::RARα translocations and acute myeloid leukemia with KMT2A::MLLT3 (MLL::AF9) fusions, f-circRNAs can be oncogenic or sustain the oncogenic properties of chimeric proteins." (PMID 36585787, 2023). "Variability in its efficacy is prominently observed in some cancerous disease models, such as acute promyelocytic leukemia (APL), which is characterized by truncated retinoic acid receptor alpha (RAR-α)." (PMID 36365229, 2022). "PML derived its name due to the discovery that over 90% of patients with acute promyelocytic leukemia (APL) harbor a chromosomal translocation, which joins the PML gene with the gene encoding the retinoic acid receptor alpha (RARα)." (PMID 36230470, 2022).